SOST (sclerostin)
Diseases named in the same sentence as SOST in open-access papers (continued):
Sharing a sentence is not in itself a finding about the gene and the disease.
immunodeficiency (1 paper, 2021). Failure of the immune system to protect the body adequately from infection, due to the absence or insufficiency of some component process or substance. "Although sclerostin has been proven to participate in normal B cell development and differentiation, in the case of immune diseases, the research on the applications of monoclonal sclerostin antibody is still mainly limited to its influence on bone formation." (PMID 33717084, 2021). "Moreover, knowledge about the roles of sclerostin in immune diseases is still limited, which needs further in-depth research." (PMID 33717084, 2021). "Therefore, immunodeficiency might occur in the patients receiving sclerostin antibodies treatment, which should deserve more attention." (PMID 33717084, 2021).
peripheral neuropathy (1 paper, 2025). A disorder affecting the peripheral nervous system. "Moreover, residual confounding by unmeasured comorbidities (i.e., peripheral neuropathy and microvascular disease) or lifestyle factors (e.g., physical activity, dietary patterns) might influence both sclerostin levels and the risk of PAD." (PMID 40731833, 2025).
SOST also shares sentences with these, for which no sentence is quoted: multiple myeloma (27 papers); chronic periodontitis (8); genetic disorders (8); liver disease (6); end-stage renal disease (5); X-linked hypophosphatemia (5); hypogonadism (4); abdominal aortic aneurysm (3); kidney (3); melanoma (3); Paget’s disease of bone (3); cognitive decline (2); hematological diseases (2); juvenile idiopathic arthritis (2); leukemia (2); non-alcoholic fatty liver disease (2); osteoporosis-pseudoglioma syndrome (2); polycystic ovary syndrome (2); psoriatic arthritis (2); pycnodysostosis (2); systemic lupus erythematosus (2); thalassemia (2); acute myocardial infarction (1); alcoholism (1); ameloblastoma (1); amyloid (1); ankylosis (1); Anxiety (1); Aortic dissection (1); autoimmune disease (1).
A further 71 diseases each share a sentence with SOST in 1 paper.